RELN (reelin)
Diseases named in the same sentence as RELN in open-access papers (continued):
Sharing a sentence is not in itself a finding about the gene and the disease.
dementia (13 papers, 2013 to 2025). Loss of intellectual abilities interfering with an individual's social and occupational functions. "This genetic variant in a case protected from ADAD suggests a role for RELN signaling in resilience to dementia." (PMID 37497015, 2023). "A genetic variant in a case protected from ADAD suggests a role for RELN signaling in resilience to dementia." (PMID 37188781, 2023). "Previous studies from our group have demonstrated increases in reelin protein and mRNA levels in brain frontal cortex extracts from AD patients and individuals with dementia associated with Down syndrome." (PMID 35886870, 2022). "Several studies have shown that reelin deficiency may accelerate learning and memory impairment, which accompanies dementia and other aging-related diseases." (PMID 38792614, 2024). "Here, we aimed to investigate whether a similar Reelin-associated neuropathology is observed in the aged human hippocampus and whether it correlated with dementia status." (PMID 24252415, 2013). "Growing evidence sustains the interaction between Reelin signal components and the few molecules related to AD, Parkinson’s disease and dementia." (PMID 40867631, 2025). "For CSF, Reelin levels decreased in the CSF of dementia cases compared to controls and MCI patients." (PMID 32438605, 2020). "These Reelin changes correlate with observed levels of amyloid β-protein and pTau in the CSF of dementia and control cases." (PMID 32438605, 2020). "In this study, we analyzed brain levels of RELN mRNA and Reelin protein in post-mortem frontal cortex samples from different sporadic AD stages, Parkinson’s disease with dementia (PDD), and Creutzfeldt-Jakob disease (sCJD), obtained from five different Biobanks." (PMID 32438605, 2020). "They demonstrated that ApoE4, which is associated with an earlier average age at onset of dementia, depletes ApoER2 from the neuronal surface after ligand-induced endocytosis by Reelin, which impairs synaptic plasticity and NMDA phosphorylation induced by Reelin." (PMID 27803648, 2016). "Herein, three cohorts of biosamples collected from subjects with ERM who had undergone phaco-vitrectomy were examined for their simultaneous expression of Reelin, in concert with Aβ1-42, FTH1 and TAU, also known as candidate hallmarks of cognitive decline (dementia and AD)." (PMID 40867631, 2025). "Regulation of this RELN-protective pathway, particularly in the ERC, may have a profound therapeutic impact on the resistance to Tau pathology and neurodegeneration, and resilience against cognitive decline and dementia in AD." (PMID 37188781, 2023). "Stereological analyses indicated that their density in the hippocampal formation is largely independent of the dementia status; however, it revealed a trend towards higher levels in patients with AD and a putative link to alterations in Reelin proteolytic processing." (PMID 24252415, 2013). "However, we feel that the CSF Reelin changes observed between MCI, patients with dementia, and sCJD might be helpful in generating a biomarker signature in prodromal studies of unidentified dementia and sCJD." (PMID 32438605, 2020). "We analyzed the RELN and Reelin levels in brain samples of AD(III-IV) and AD(V-VI), Parkinson’s disease with dementia (PDD), and sCJD cases compared to non-degenerative (nND) samples." (PMID 32438605, 2020).
atherosclerosis (10 papers, 2015 to 2025). A disease characterized by the build-up of fatty material and calcium deposition in the arterial wall resulting in partial or complete occlusion of the arterial lumen. "Recent research has implicated the pharmacological depletion of circulating Reelin inhibits the atherosclerosis progression." (PMID 41531492, 2025). "Reelin signaling is implicated in increased endothelial-leukocyte adhesion and macrophage accumulation in lesions and the development of atherosclerosis." (PMID 37408206, 2023). "Considering that atherosclerosis can further aggravate arrhythmia, a pathophysiological change associated with MI, it may be beneficial to therapeutically obstruct the interaction between reelin and ApoER2." (PMID 38178871, 2023). "In this context, recent research places Reelin in peripheral inflammation: Hepatocyte- derived Reelin increases leukocyte adhesion and NF-κB activation especially in vascular conditions like atherosclerosis, rheumatoid arthritis, and multiple sclerosis." (PMID 41416042, 2025). "Taken together, these results suggest Reelin as a promoter and biomarker of endothelial dysfunction and potentially of inflammation, which is activated during inflammatory diseases such as atherosclerosis, multiple sclerosis, and now COVID-19." (PMID 37441066, 2023). "In atherosclerosis or multiple sclerosis, Reelin promotes inflammatory cell recruitment and inflammation by increasing the expression of leukocyte-endothelial adhesion markers (E-selectin, ICAM-1, and VCAM-1) on endothelial cells." (PMID 37441066, 2023). "First, we have demonstrated in models of atherosclerosis, multiple sclerosis (MS), and COVID-19 that plasma Reelin inactivation reduces inflammatory cell recruitment by decreasing the expression of leukocyte–endothelial adhesion proteins (E-selectin, ICAM-1, and VCAM-1)." (PMID 38607022, 2024). "Previous research has linked elevated Reelin levels to increased vascular inflammation and atherosclerosis, suggesting that targeting Reelin could be a novel strategy for cardiovascular disease prevention." (PMID 39727958, 2024). "The ability to selectively modulate Reelin levels in the periphery opens avenues for exploring its therapeutic potential in diseases characterized by compromised endothelial function, such as atherosclerosis, multiple sclerosis, and even severe inflammatory conditions like COVID-19." (PMID 38607022, 2024). "While reelin can restore heart function by preventing adverse cardiac remodeling after injury, its interaction with ApoER2 in the aorta can promote the vascular adhesion of leukocytes, contributing to the development of atherosclerosis." (PMID 38178871, 2023). "As the full length reelin (~400-kd) or its central fragment R3-6 (340 kd) is too large to be used in gene transfer studies, the reelin subregion R5-6 (~88kd) could be a valuable tool in future studies for investigating the effect of VLDLR/apoER2 on atherosclerosis in animal models." (PMID 26317415, 2015).
glioblastoma (10 papers, 2020 to 2025). The most malignant astrocytic tumor (WHO grade IV). "Strikingly, within glioblastoma, a tumor that, despite intensive therapy, presents with an average patient survival of 18 months, reelin expression was clearly associated with increased survival." (PMID 38543187, 2024). "The data presented in this work strongly suggest that reelin might be a potential modulator of underlying molecular mechanisms that contribute to glioblastoma invasion." (PMID 38543187, 2024). "Interestingly, the expression of reelin is negatively associated with tumor grade and, within glioblastoma, correlates with increased overall survival." (PMID 38543187, 2024). "Using four established cell lines, we next investigated the potential underlying effects reelin has on glioblastoma cell behavior that might account for the striking differences in patient survival." (PMID 38543187, 2024). "To ascertain the potential role of reelin in glioblastoma cell invasion, we broke down this highly complex process into several key aspects, namely cell attachment, cell detachment, cell transmigration through an existing matrix, and locomotive capacity." (PMID 38543187, 2024). "All these aspects investigated are closely associated with the invasive capacity of cells; therefore, we conclude that reelin, within a fibronectin matrix, has antiinvasive properties with respect to glioblastoma cells." (PMID 38543187, 2024). "In glioblastoma, the expression of reelin is regularly downregulated by promoter methylation, which, in turn, is associated with a more aggressive phenotype of the tumor and leads to a poorer prognosis for the patient." (PMID 38543187, 2024). "To further elucidate a potential biological reason for these findings, we looked at the cellular behavior of glioblastoma cell lines grown on a pure fibronectin matrix or a matrix with reelin inserts." (PMID 38543187, 2024). "If the reduction in reelin expression in glioblastoma is of clinical relevance, this should be mirrored in relative patient survival." (PMID 38543187, 2024). "The proliferation of glioblastoma cells were reduced by RELN signaling depending on mutant DAB1 stimulation." (PMID 37491836, 2023). "It is speculated that RELN may mediate cell–cell signaling, cell migration, or other related biological processes in glioblastoma cells by binding to its receptor ITGB1." (PMID 40149878, 2025). "Here, we postulate that reelin, probably the 180 kDa isoform of reelin, might also be utilized in the Alcatraz Strategy, as it seems that the incorporation of reelin into a matrix can impair the interaction of glioblastoma cells with their microenvironment." (PMID 38543187, 2024). "To this end, we utilized four independent data sets and could identify a positive correlation between reelin expression and overall patient survival in the context of glioblastoma." (PMID 38543187, 2024). "Additionally, studies have shown that the development and migration of glioblastomas are modulated by RELN signaling." (PMID 40217319, 2024). "As reelin is predominantly described, at least in the context of the brain, as a neuronal stop signal, we focused our analyses on glioblastoma, a grade IV astrocytoma, the most aggressive brain tumor in adults, which is characterized by its highly motile nature." (PMID 38543187, 2024). "In summary, glioblastoma cells exhibited less invasive behavior in the presence of reelin." (PMID 38543187, 2024). "While our study has clear limitations, such as the use of established cell lines and not primary patient material, it nevertheless clearly shows that further investigations into the potential use of reelin as a putative stop signal for glioblastoma invasion are warranted." (PMID 38543187, 2024). "However, stimulating Reelin signaling showed that the proliferation of tumor cells in glioblastoma decreased significantly." (PMID 34485127, 2021).
glioblastoma (continued). "For example, an alternative explanation for the reduced presence of reelin messenger RNA in glioblastoma could be the high percentage of TAMs (tumor-associated macrophages) in glioblastoma, which have not been reported to express reelin so far." (PMID 38543187, 2024). "This project is designed to investigate whether the natural properties of reelin can be harvested as part of an anti-invasive strategy that reduces the invasive potential of glioblastoma cells and turns the malignancy into a more localized and easier-to-treat disease." (PMID 38543187, 2024). "Also, in glioblastoma, the expression of Reelin was positively related to survival." (PMID 34485127, 2021). "These pathways, which are linked to tumor progression, underscore the potential roles of RELN and GSTO2 in glioblastoma biology." (PMID 40171042, 2025). "The expression levels of RELN and GSTO2 were significantly lower in glioblastoma samples compared to controls." (PMID 40171042, 2025). "By intersecting the results of these methods, two genes, RELN and GSTO2, emerged as shared biomarkers between glioblastoma and degenerative CNS diseases." (PMID 40171042, 2025). "Similarly, expression levels of RELN and GSTO2 significantly decreased glioblastoma samples compared to controls." (PMID 40171042, 2025). "The relationship between these pathways and hub gene expression is further depicted in a heatmap for intuitive visualization, supporting the hypothesis that RELN and GSTO2 are critical mediators at the intersection of glioblastoma and degenerative CNS disease mechanisms." (PMID 40171042, 2025). "Choosing fibronectin, a protein we had previously shown to be secreted by glioblastoma cells and utilized as a survival aid, as a basis for the matrix, we compared the behavior of cells interacting with fibronectin with or without reelin inserts." (PMID 38543187, 2024). "These analyses strongly suggest that either reelin expression is a potential biomarker for glioblastoma patient survival, independent of the protein’s actual function, or that reelin might have a therapeutically relevant effect on glioblastoma cell behavior." (PMID 38543187, 2024).
neuroblastoma (10 papers, 2017 to 2024). Neuroblastoma (NB) is the most common solid, extracranial childhood tumor. "Previous studies have revealed that Reelin is downregulated in pancreatic cancer, colorectal cancer, and neuroblastoma." (PMID 36568166, 2022). "However, as compared with all the other lesions, sporadic adenocarcinoma has the highest ApoER2 mRNA expression, suggesting that, in this adenocarcinoma, ApoER2 acts as a negative regulator of reelin, as previously shown in neuroblastoma cells." (PMID 36290310, 2022). "Up-regulation of miR-128 inhibited Reelin and DCX expression and then reduced neuroblastoma cell notility and invasiveness." (PMID 28146425, 2017). "Moreover, miR-128 upregulation inhibits Reelin and DCX expression leading to impairment of neuroblastoma cell motility and invasiveness." (PMID 32993809, 2020).
temporal lobe epilepsy (10 papers, 2015 to 2025). A localization-related (focal) form of epilepsy characterized by recurrent seizures that arise from foci within the temporal lobe, most commonly from its mesial aspect. "In patients with temporal lobe epilepsy, reduced reelin gene expression has been associated with disrupted compact cell layering, suggesting that decreased reelin signaling may contribute to morphological abnormalities in the temporal cortex." (PMID 40548070, 2025). "The remaining three genes KMT2C, RELN, and BRCA2, had been previously associated with Kleefstra syndrome (OMIM #617768), Familial Temporal Lobe Epilepsy (OMIM #616436), and with different types of cancer, respectively." (PMID 36568968, 2022). "Interestingly, our previous study has shown that granule cell dispersion in temporal lobe epilepsy patients is due to reduced Reelin expression by GABAergic interneurons." (PMID 32903462, 2020). "In temporal lobe epilepsy (TLE), reelin gene hypermethylation disrupts the dispersion of granule cells and the expression of reelin." (PMID 39376563, 2024).
Ataxia (9 papers, 2014 to 2023). Ataxia refers to impaired coordination of voluntary muscle movement. "The link between Reelin and ataxia comes from the observation of the ataxia phenotype in a mouse model of Reelin deficiency, the reeler mouse." (PMID 37891846, 2023). "The RELN gene has been widely explored and several mutations have been reported in mice and rats that are associated with the “reeler phenotype”, which results in abnormal locomotor behaviors such as tremors, dystonia, and ataxia." (PMID 38082412, 2023). "The ectopic expression of Reelin in the cerebellum of reeler mice induced the restoration of the tyrosine phosphorylation of Dab1, which was sufficient to rescue purkinje cells’ migration and was associated with the partial rescue of the ataxia phenotype." (PMID 37891846, 2023). "Defects in reelin signaling results in cerebellar dysfunction leading to ataxia as seen in the Reeler mouse." (PMID 32244519, 2020). "The role of the Reelin pathway in neuronal migration has been extensively studied and in humans homozygous mutations in the RELN gene are associated with ataxia, cognitive abnormalities and cerebellar hypoplasia." (PMID 30618631, 2018). "Under this perspective, it is of relevance that the ectopic expression of Reelin in Reeler mice rescued animals from cerebellar ataxia, and supported a substantial recovery in granule cell proliferation." (PMID 27252624, 2016). "Reelin has also been evidenced as a target in spinocerebellar ataxia." (PMID 37891846, 2023). "In humans, loss of VLDLR results in a non-progressive cerebellar ataxia phenotype and mutations in RELN cause cerebellar hypoplasia similar to that of the Reeler mouse." (PMID 32244519, 2020). "Reelin could thus lead to novel strategies for treating ataxias." (PMID 31969808, 2019).
cognitive decline (9 papers, 2017 to 2025). "We and others have established that Reelin deficiencies in the brain are correlated to higher cognitive decline in AD patients as well as AD mouse models, indicating essential functions in neurons." (PMID 37441066, 2023). "Lower CSF levels of all biomarker candidates, except RELN, were associated with more pronounced cognitive decline." (PMID 35602555, 2022). "Research indicates that RELN expression is typically decreased in these diseases, contributing to pathological processes such as the loss of neuronal connectivity, neuronal death, and cognitive decline." (PMID 40171042, 2025). "In AD and other neurodegenerative disorders, reduced RELN signaling can alter synaptic structure and function, affecting neural network stability and plasticity, leading to cognitive decline." (PMID 40171042, 2025). "The RELN-COLBOS variant was only found in the individual and his sister, who also had late-onset cognitive decline." (PMID 37188781, 2023). "A female sibling carrier of the RELN-COLBOS and PSEN1-E280A variants also presented with delayed age at onset of cognitive decline, although with less optimal protection compared to her brother and prolonged end-stage disease." (PMID 37188781, 2023). "Several reports support a protective role of Reelin in preventing cognitive decline in AD and tauopathy mouse models." (PMID 32438605, 2020). "Alterations in reelin expression, which forms amyloid deposits in AD, may contribute to cognitive decline by impairing neuronal plasticity." (PMID 40497980, 2025). "In addition, Reelin generated under these conditions is not functional, as it is in AD, which might enhance cognitive decline and disease progression." (PMID 32438605, 2020).
gastric cancer (9 papers, 2017 to 2026). A primary or metastatic malignant neoplasm involving the stomach. "Reelin is weakly expressed in gastric cancer, due to the aberrant hyper-methylation of the reelin-encoding gene promoter." (PMID 28255385, 2017). "Two of the forty-three breakend SVs found in all members of the LRLS group had a potential impact on RELN, a gene correlated to several cancers including gastric cancer according to OncoKB Cancer Genes list database." (PMID 37627102, 2023). "RELN (Reelin), a key regulator of neuronal migration, is frequently epigenetically silenced in different cancers, including pancreatic, breast and gastric cancer." (PMID 36703611, 2023). "Two SVs (7_103463079_103463080_BND_1 and 7_103463462_103463463_BND_1) were found to be related to the intronic region of the RELN gene, which has been correlated to several cancer risks including gastric cancer." (PMID 37627102, 2023). "The two loci (DOCK10 and FCN1-FCN2) replicated from CoGaPro1, and the 11 loci replicated from CoGaPro2 (CDK15, CROCC2-SNED1, TLR2-RNF175-SFRP2, WWC2, RELN, ZMYM5-ZMYM2, KLF12, SKAP1, CABLES2, and MIR630) gave further support for these genes being associated with a risk of CRC and gastric cancer." (PMID 41516419, 2026). "Suppressed RELN expression has been observed in breast, pancreatic and gastric cancers." (PMID 34639052, 2021).